NDUFAF7 (NADH:ubiquinone oxidoreductase complex assembly factor 7)
Description:
Arginine methyltransferase involved in the assembly or stability of mitochondrial NADH:ubiquinone oxidoreductase complex (complex I). Acts by mediating symmetric dimethylation of 'Arg-118' of NDUFS2 after it assembles into the complex I, stabilizing the early intermediate complex.
Synonyms: C2orf56; PRO1853; MidA
Tractability: PROTAC: ubiquitination databases record sites on it; its protein half-life has been measured.
Gene: Protein-coding gene on chromosome 2 (37,231,631 to 37,253,403, forward strand). Ensembl gene ENSG00000003509.
Subcellular location: Mitochondrion
Pathways (Reactome):
Metabolism: Complex I biogenesis
Gene Ontology:
Molecular function: enzyme binding; protein binding; protein-arginine omega-N symmetric methyltransferase activity; methyltransferase activity
Biological process: mitochondrial respiratory chain complex I assembly; peptidyl-arginine methylation, to symmetrical-dimethyl arginine
Cellular component: extracellular region; mitochondrion; mitochondrial matrix
Genetic constraint (gnomAD): Loss-of-function variants: 46 observed, 43.84 expected, observed/expected ratio (o/e) 1.05, 90% interval 0.83 to 1.34. The upper end of that interval is the gene's LOEUF score, 1.34, which puts it in group 5 of 6, group 1 being the genes least tolerant of losing a copy. Missense variants: 602 observed, 528.01 expected, observed/expected ratio (o/e) 1.14, 90% interval 1.07 to 1.22. Synonymous variants: 211 observed, 190.29 expected, observed/expected ratio (o/e) 1.11, 90% interval 0.99 to 1.24.
Gene-disease validity (ClinGen):
ClinGen rates the evidence that NDUFAF7 causes each of these diseases.
mitochondrial disease (autosomal dominant): Disputed.
Homologues: Orthologues: chimpanzee NDUFAF7 (99% identical), macaque NDUFAF7 (97% identical), dog NDUFAF7 (87% identical), pig NDUFAF7 (87% identical), guinea pig NDUFAF7 (86% identical), mouse Ndufaf7 (83% identical), rat Ndufaf7 (75% identical), rat AABR07025743.1 (73% identical), zebrafish ndufaf7 (57% identical), tropical clawed frog ndufaf7 (57% identical), Drosophila melanogaster CG17726 (43% identical), Caenorhabditis elegans ZK1128.1 (35% identical).
Diseases named in the same sentence as NDUFAF7 in open-access papers:
NDUFAF7 is named in the same sentence as 8 diseases in open-access papers, as found by Europe PMC text mining. Sharing a sentence is not in itself a finding about the gene and the disease. The quoted sentences say what the papers report.
Alzheimer disease (3 papers, 2021 to 2024). A progressive, neurodegenerative disease characterized by loss of function and death of nerve cells in several areas of the brain leading to loss of cognitive function such as memory and language. "Over-expression of the target protein amyloid precursor protein (APP) gene caused by exon variants of NDUFAF7 is associated with the risk of Alzheimer’s disease." (PMID 38783263, 2024). "We targeted NDUFS3 and NDUFAF7 because these genes localize to genetic loci associated with increased risk of Alzheimer’s disease." (PMID 37171075, 2023). "The NDUFS3 and NDUFAF7 genes are encoded in loci that increase Alzheimer’s disease risk." (PMID 37171075, 2023). "Here, we add six variants associated with Alzheimer’s disease risk (near APP, CHRNE, PRKD3/NDUFAF7, PLCG2 and two exonic variants in the SHARPIN gene)." (PMID 34099642, 2021).
COVID-19 (3 papers, 2020 to 2023). A disease caused by infection with severe acute respiratory syndrome coronavirus 2. "Genes impacting mitochondrial function include 31 of 37 in mitochondrial DNA and nuclear genes encoding mitochondrial proteins, including ten EDS-related (NDUFA-11/S3, OPA1, TYMP, etc.)and three COVID-19-related (STAT2, TLR3, NDUFAF7) genes." (PMID 37504295, 2023). "The analysis identified genes harboring deleterious mutations (according to the DANN score) with a statistically significant higher frequency in controls than in COVID-19 patients such as the olfactory receptor gene OR4C5 (adjusted p-value of 1.5E-10), and NDUFAF7, although to a lesser extent." (PMID 33206719, 2020).
myopia (3 papers, 2018 to 2023). "Another study demonstrated that a variant of the NDUFAF7 gene that might contribute to the development of pathological myopia by decreasing complex I activity resulted in decreased ATP and GTP production downstream, which weakened photoreceptor cell function." (PMID 38136985, 2023). "For example, a mutation in the gene NDUFAF7, which encodes a mitochondrial reduced nicotinamide adenine dinucleotide (NADH) dehydrogenase complex assembly factor, was associated with pathological myopia in humans, implicating mitochondrial dysfunction in refractive error development." (PMID 30300342, 2018).
cancer (1 paper, 2021). A tumor composed of atypical neoplastic, often pleomorphic cells that invade other tissues. "Particularly, an increase of proteins involved in redox balance, antioxidant defenses (CS, NDUFAF7, UQCRC2) and mitochondrial morphology (IMMT) was observed while cancer promotion proteins (DIABLO, TCPT) decreased." (PMID 33801925, 2021).
NDUFAF7 also shares sentences with these, for which no sentence is quoted: infection (1 paper); Iron deficiency (1); osteosarcoma (1); pathologic myopia (1).